GAS6 (growth arrest specific 6)
Diseases named in the same sentence as GAS6 in open-access papers (continued):
Sharing a sentence is not in itself a finding about the gene and the disease.
helminth infections (2 papers, 2020 to 2025). "Interestingly, CD4 + IL-10+-producing cells from MS patients with helminthic infection showed higher levels of GAS6 expression than Th17 cells, and GAS6 blockade induced an expansion of Th17 effector genes." (PMID 40231720, 2025). "We discovered that CD4+ T cells from patients with MS and concurrent natural helminth infections (HIMS) contained a lower percentage of Th17 cells as well as lineage-specific related genes and dampened DCs activation in a GAS6-dependent manner." (PMID 33347509, 2020). "We show here that patients with concurrent natural helminth infections and MS condition (HIMS) had an increased expression of the negative regulatory TAM receptors in antigen-presenting cells and their agonist GAS6 in circulating CD11bhigh and CD4+ T cells compared to patients with only MS." (PMID 33347509, 2020).
intestinal tumor (2 papers, 2017 to 2021). "Moreover, the inhibitory mechanism of Gas6/TAM in intestinal tumors has also been gradually discovered." (PMID 33509214, 2021). "The inhibitory effect of Gas6 on intestinal tumors may be related to the suppression of colonic stromal cellular immune response." (PMID 33509214, 2021).
invasive breast carcinoma (2 papers, 2020). A carcinoma that infiltrates the breast parenchyma. "Given the higher levels of Gas6 in normal breast and DCIS, and reduction of Gas6 in invasive breast cancer, most prominently in several subtypes known to be aggressive, we asked whether Gas6 was associated with patient survival or prognosis." (PMID 32352034, 2020). "Analysis of tissue microarrays showed that Gas6 was highly expressed in ductal carcinoma in situ (DCIS) but markedly decreased in invasive breast cancer." (PMID 32352034, 2020). "Gas6 produced by macrophages is essential for the transition of premalignant to invasive breast cancer." (PMID 31963783, 2020).
ischemia (2 papers, 2022 to 2024). A hypoperfusion of the BLOOD through an organ or tissue caused by a PATHOLOGIC CONSTRICTION or obstruction of its BLOOD VESSELS, or an absence of BLOOD CIRCULATION. "Based on our findings, we suggest that paeoniflorin is potentially effective in alleviating radiation enteritis via the activation of the Gas6/Axl/SOCS3 axis and subsequent reduction in intestinal inflammation and ischemia." (PMID 35359871, 2022). "GAS6 has not been previously proposed as a serological marker of CCC in patients with ischemia." (PMID 39195894, 2024).
kidney damage (2 papers, 2019 to 2021). "In particular, we asked whether improved kidney damage following Gas6 administration was associated to the activation of Axl, MerTK or both." (PMID 33803290, 2021). "On the contrary, they observed decreased levels of Gas6 in diabetic patients suffering from the underestimated nephropathy and have proposed Gas6 (cutoff~9 ng/mL) as a better biomarker than cystatin C and creatinine." (PMID 31485279, 2019).
kidney failure (2 papers, 2010 to 2013). An acute or chronic condition that is characterized by the inability of the kidneys to adequately filter the blood. "Gas6 and sAxl are increased during organ failure, and Gas6 is increased in patients receiving intensive care or experiencing kidney failure, again indicating that Gas6 is increased in severe inflammatory states." (PMID 20731857, 2010). "Gas6 was higher in patients with organ failure, kidney failure and in patients receiving intensive care, whereas sAxl was higher in patients with organ failure." (PMID 20731857, 2010).
liver cancer (2 papers, 2020 to 2024). An epithelial or non-epithelial malignant neoplasm that arises from the liver. "Next, we investigated which Gas6/Axl-mediated pathways promote the invasive phenotype of liver cancer cells." (PMID 38673795, 2024). "Studies have shown that Gas6 and Axl are highly expressed in gastric, ovarian, and liver cancers, among many others, and patient prognosis is negatively correlated with Gas6/Axl complex levels." (PMID 32432570, 2020).
liver dysfunction (2 papers, 2020 to 2022). "Preoperatively elevated sAXL and GAS‐6 levels predicted postoperative liver dysfunction (area under the curve = 0.721 and 0.722; P < 0.005) and worse clinical outcome." (PMID 34951136, 2022).
lupus nephritis (2 papers, 2019 to 2024). Glomerulonephritis in the context of systemic lupus erythematosus. "Gas6 activation of the mesangial Axl receptor has been implicated in the development of glomerular damage in several GN, including diabetic nephritis, lupus nephritis, and IgA nephropathy." (PMID 31360267, 2019). "Interestingly, lupus nephritis patients with higher sMer, sAxl, and Gas6 levels tended to suffer from proliferative GN." (PMID 31360267, 2019). "Targeting the Gas6/Axl pathway is a promising therapeutic strategy for lupus nephritis." (PMID 31360267, 2019). "We have demonstrated a critical role for the Gas6/Axl pathway in mouse models of lupus nephritis." (PMID 31360267, 2019). "Gas6 may also serve as a biomarker for SLE therapeutics, especially in lupus nephritis." (PMID 31360267, 2019). "In summary, the significance of plasma levels of Gas6 or ProS in SLE patients is complex and may depend on SLE activity and severity and may also be influenced by other clinical parameters, including lupus disease manifestations (lupus nephritis, vasculitis, arthritis, etc.)." (PMID 31360267, 2019).
metastatic cancer (2 papers, 2006 to 2022). A carcinoma which has spread from the original site of growth to another anatomic site. "Examples of these unique genes include Serpine2, which is overexpressed in metastatic cancer; Ctnnb1, Fliih, Pdlim4/Ril, all of which affect migratory behavior of cells; and Gas6, which is a ligand for the Axl oncogene." (PMID 17147824, 2006). "In line with our previous colony formation experiments, we found an increase in proliferating metastatic cancer cells (MUC1+Ki67+) in gemcitabine treated PCLS cultures supplemented with recombinant Gas6 compared with gemcitabine treated PCLS cultures lacking recombinant Gas6." (PMID 35022267, 2022).
metastatic prostate carcinoma (2 papers, 2016 to 2022). A carcinoma that arises from the prostate gland and has spread to other anatomic sites. "AXL was shown to be highly expressed in metastatic prostate cancer and its interaction with Gas6 was suggested to play a role in establishing tumor dormancy in the bone marrow microenvironment." (PMID 26762579, 2016). "Of note, hypoxia may not only act on transcriptional regulation of AXL but also stabilize GAS6/AXL signaling by preventing GAS6-mediated downregulation of AXL, at least in DU145 and PC3 metastatic prostate cancer cell lines." (PMID 35572601, 2022).
microcephaly (2 papers, 2023 to 2025). A congenital or acquired developmental disorder in which the circumference of the head is smaller than normal for the person's age and sex. "Unlike DENV and West Nile (WNV) flaviviruses that use the TIM1 receptor for infection as well but do not cause microcephaly, ZIKV can efficiently use Axl to infect fetal endothelial cells by preferentially binding the Axl ligand Gas6 (Growth Arrest-Specific 6)." (PMID 36680287, 2023).
oral cancer (2 papers, 2017 to 2021). "The in vitro experiment remodeling the tumor environment confirmed the mutual promoting effect between oral cancer cells and TAMs, and the Gas6/Axl signaling pathway was further confirmed to enhance the epithelial-mesenchymal-transition of oral cancer cells." (PMID 34497832, 2021). "Overexpression of GAS6 can promote migration and invasion of oral cancer cells." (PMID 28286742, 2017).
Oral Squamous Cell Carcinoma (2 papers, 2015 to 2019). "This study explored the level and clinical significance of serum Gas6 in patients with oral squamous cell carcinoma (OSCC)." (PMID 26207647, 2015). "Studies have shown that Gas6 and Anexelekto (Axl) are highly expressed in oral squamous cell carcinoma (OSCC) and other cancer tissues and cells and the binding of Gas6 and Axl affects cell migration and other functions." (PMID 31110076, 2019).
ovarian endometriosis (2 papers, 2008 to 2025). A non-neoplastic disorder characterized by the growth of endometrial tissue in the ovaries. "Published studies have identified GAS6 as an important hub gene associated with the pathophysiology of ovarian endometriosis, with significantly higher expression in ectopic versus eutopic tissue and with good diagnostic properties (AUC > 0.8)." (PMID 40943271, 2025). "GAS6 was also associated with efferocytosis in ovarian endometriosis lesions compared with eutopic endometrium." (PMID 40943271, 2025). "In addition to its association with efferocytosis in ovarian endometriosis, GAS6 was significantly upregulated in ectopic versus eutopic tissue, and further univariate analysis showed good diagnostic properties with an AUC > 0.8." (PMID 40943271, 2025). "Overexpression of both AXL and GAS6 in ovarian endometriosis has previously been demonstrated using RT-PCR analysis and IHC." (PMID 19055724, 2008).
pneumonia (2 papers, 2020 to 2021). An acute, acute and chronic, or chronic inflammation focally or diffusely affecting the lung parenchyma, caused by an infection in one or both of the lungs (by bacteria, viruses, fungi, or mycoplasma.). "Thus, TSG-6 activates STAT6 to induce Gas6 expression in AMs for the ALI resolution during pneumonia." (PMID 32849610, 2020).
preeclampsia (2 papers, 2022 to 2025). Preeclampsia is a hypertensive disorder of pregnancy that is characterized by new-onset hypertension with proteinuria presenting after 20 weeks of gestation, and depending on mild or severe forms may initially present with severe headache, visual disturbances, and hyperreflexia. "It has been shown that plasma Gas6 concentrations were significantly lower in patients with preeclampsia (PE) as compared to normotensive pregnant (NP) women." (PMID 35627905, 2022). "Preeclampsia (PE) was induced in pregnant rats through an 11-day treatment with Gas6." (PMID 39996749, 2025). "Dysregulated Gas6/AXL signaling disrupts placental function by impairing trophoblast invasion, intensifying inflammation, and increasing oxidative stress—key hallmarks of preeclampsia." (PMID 39996749, 2025).
Prostate tumor (2 papers, 2016 to 2023). "Prostate tumor-associated macrophages can promote the growth of PCa, and secreted Gas6 can further enhance the activation of RON and AXL receptors in PCa cells, thereby driving CRPC." (PMID 37143720, 2023). "We have also demonstrated that GAS6 secreted from osteoblasts in the bone marrow environment plays a critical role in establishing prostate tumor cell dormancy." (PMID 27028863, 2016). "We have demonstrated that activation of Axl on PCa cells by GAS6 from osteoblasts in the bone marrow environment plays a critical role in establishing prostate tumor cell dormancy." (PMID 27028863, 2016).
renal dysfunction (2 papers, 2023 to 2025). "Nevertheless, GAS6 was found to be negatively associated with eGFR, and significantly elevated in AHF patients with renal dysfunction, especially in dead patients." (PMID 36635690, 2023). "GAS6 may prove to be a novel and additional clinical biomarker for risk stratification of AHF patients, especially in the cohort with renal dysfunction." (PMID 36635690, 2023). "Furthermore, we also revealed that AHF patients with renal dysfunction had higher plasma GAS6 levels." (PMID 36635690, 2023). "In this regard, AHF patients with renal dysfunction whose circulating GAS6 levels may indicate a primary inflammatory/fibrotic susceptibility may benefit from optimization of anti-inflammatory/antifibrosis therapies, such as mineralcorticoid receptor antagonists." (PMID 36635690, 2023). "We also found that higher levels of GAS6 and clinical biomarkers, including NT-proBNP, TnT, BUN and CRP, were accompanied by highest mortality in AHF patients, especially in those with renal dysfunction." (PMID 36635690, 2023).
Respiratory syncytial virus infection (2 papers, 2022). "In addition, it has been shown that Gas6 is a key regulator of antimicrobial immunity after primary respiratory syncytial virus infection." (PMID 35682869, 2022).
retinal degeneration (2 papers, 2014 to 2021). Degeneration of the retina. "We have previously shown that Tyro3 mouse mutants, Gas6 mouse mutants, and retina-specific Pros1 mouse mutants all have a normal number of PRs at this time; but that Gas6/Pros1 double mutants display PR death and retinal degeneration that fully phenocopies the degeneration of the Mertk mutants." (PMID 25265470, 2014).
Retinal dystrophy (2 papers, 2013 to 2021). Retinal dystrophy is an abnormality of the retina associated with a hereditary process. "Additionally, we assessed whether Gas6 NPs enhanced the therapeutic effects of gene therapy in RCS rat model of MERTK-associated retinal dystrophy." (PMID 34970569, 2021). "MERTK is a receptor tyrosine kinase belonging to the TAM receptor family (Tyro-3, Axl, Mer), whose ligands include the vitamin K-dependent proteins growth arrest-specific protein 6 (gas6) and protein S, as well as the retinal dystrophy-gene products Tulp1 and Tubby." (PMID 23390493, 2013).
retinitis pigmentosa (2 papers, 2017 to 2021). Retinitis pigmentosa (RP) is an inherited retinal dystrophy leading to progressive loss of the photoreceptors and retinal pigment epithelium and resulting in blindness usually after several decades. "In mice, it has already been shown that absence of both ligands of the RTK MerTK (Mer tyrosine kinase proto-oncogene; OMIM*604705), Gas6 and ProS, leads to retinitis pigmentosa." (PMID 28125048, 2017). "However, it has been reported that Gas6 is a multi-functional circulating protein with multiple roles related to inflammation the and immune system, and retinitis pigmentosa is usually accompanied by inflammation." (PMID 34970569, 2021).
synovitis (2 papers, 2023). Inflammation of a synovial membrane. "Interestingly, intra-articular injection of GAS6 significantly delayed synovial inflammation and cartilage destruction compared to vehicle-treated obese OA mice, manifested as lower synovitis and OARSI scores." (PMID 37144868, 2023).
systemic sclerosis (2 papers, 2020 to 2024). A chronic disorder, possibly autoimmune, marked by excessive production of collagen which results in hardening and thickening of body tissues. "In this review, we aim to elucidate the pathogenesis of systemic sclerosis and the role of the Gas6/TAM system, emphasizing why this system merits further investigation in this field." (PMID 39057085, 2024). "Furthermore, we searched the PubMed, Medline, and Cochrane libraries using the following strings: (Gas6 OR TAM receptors) AND (systemic sclerosis OR scleroderma)." (PMID 39057085, 2024).
Thrombocytopenia (2 papers, 2013 to 2022). A reduction in the number of circulating thrombocytes. "Our results show that both sMer and Gas6 concentrations were higher in patients with thrombocytopenia, PT-INR derangement and SIC." (PMID 35203408, 2022). "In the multivariate analysis, both Gas6 and sMer emerged as independent predictors of thrombocytopenia with ORs of 1.01 [95% CI 1.00–1.02] (p = 0.02) and 1.04 [95% CI 1.02–1.06] (p < 0.001), respectively." (PMID 35203408, 2022). "Patients with thrombocytopenia showed higher median values of both Gas6 (35.6 [25.9–53.8] vs. 30.7 [22.7–41.6] ng/mL; p < 0.001) and sMer (11.4 [6.4–19.2] ng/mL vs. 7.8 [3.1–13.3] ng/mL, p < 0.001) when compared to patients with a normal platelets count." (PMID 35203408, 2022). "Additionally, Gas6 independently predicted thrombocytopenia and AKI." (PMID 35203408, 2022).
acute myocardial infarction (1 paper, 2025). Necrosis of the myocardium, as a result of interruption of the blood supply to the area. "The threshold value for the Gas6/AXL complex was determined to be 1.8 ng/mL; concentrations exceeding this threshold were associated with an increased risk of myocardial infarction." (PMID 40933570, 2025). "Consequently, the implications of variations in the levels of the Gas6/AXL complex in CVD, such as acute myocardial infarction (AMI), remain largely unexplored." (PMID 40933570, 2025).
acute pancreatitis (1 paper, 2010). An acute inflammatory process that leads to necrosis of the pancreatic parenchyma. "Recently, plasma Gas6 was reported to be elevated in patients with severe sepsis, septic shock, and severe acute pancreatitis." (PMID 20637106, 2010). "Basal levels of Gas6 were low, yet it is known to be upregulated in certain states of intense inflammation such as septic shock and severe acute pancreatitis." (PMID 20637106, 2010).
agranulocytosis (1 paper, 2016). "Because Gas6 is a modulator of innate immunity, patients with HIV status, hematological malignancies, immunosuppression or agranulocytosis were excluded." (PMID 27788141, 2016).
amyloid (1 paper, 2024). "For example, in the same mouse model that we used, the AAV transduction of Gas6 alleviated the amyloid plaque load." (PMID 39200191, 2024).
aortic valve calcification (1 paper, 2019). "Administration of Raloxifene (an estrogen receptor modulator) was found to significantly decrease Gas6 levels in aortic valves of rats, with down-regulation of Gas6/Axl pathway and decreased aortic valve calcification." (PMID 30934817, 2019).
astrocytoma (1 paper, 2017). "An increased expression of GAS6 was associated with increased MERTK/AXL expression in astrocytoma patient samples." (PMID 28675785, 2017).
Atrophy (1 paper, 2013). Any weakening or degeneration, especially through lack of use. "Compared with these biomarkers, Gas6 expression was related to mesangial proliferation, but not to segmental glomerulosclerosis, endocapillary hypercellularity, or tubular atrophy/interstitial fibrosis." (PMID 23826128, 2013).
brain aneurysm (1 paper, 2023). A congenital or acquired aneurysm within the cranium. "Interestingly, microglia efferocytosis and its ability to suppress inflammation can be enhanced through the activation of AXL receptor tyrosine kinase signaling by growth arrest-specific 6 (Gas6) in a mouse model of brain aneurysm." (PMID 36994095, 2023).
brain infarction (1 paper, 2021). Tissue necrosis in any area of the brain, including the cerebral hemispheres, the cerebellum, and the brain stem. "In animal studies, administration of recombinant GAS6 significantly reduced brain infarction and neurological deficits and attenuated BBB disruption and HT." (PMID 34733281, 2021).
calcification (1 paper, 2016). Process by which organic tissue becomes hardened by the physiologic deposit of calcium salts. "Nevertheless, in all of our models, minor calcification could be induced and the lack of aggravated calcification by depletion of Gas6 does not support a major role in vascular calcification pathogenesis." (PMID 27230889, 2016).
carotid atherosclerosis (1 paper, 2017). A thickening and loss of elasticity of the walls of carotid arteries that occur with formation of atherosclerotic plaques. "The downregulation of genes for secretory leukocyte peptidase inhibitor (SLPI), uncharacterized LOC730101, and growth arrest specific 6 (GAS6) in carotid atherosclerosis associated with the symptoms of cerebral embolization in both datasets included in this study was also demonstrated." (PMID 28659610, 2017).